IL22 (interleukin 22)
Diseases named in the same sentence as IL22 in open-access papers (continued):
Sharing a sentence is not in itself a finding about the gene and the disease.
rheumatoid arthritis (continued). "For example, IL-17A and IL-22 are believed to act in concert in autoimmune pathogenesis and IL-17 has been shown to act synergistically with TNF-α, in the induction of IL-6 in rheumatoid arthritis." (PMID 34203644, 2021). "In addition, IL-22 from Th17 T cells may have an important role in the inflammatory scenario of uveitis because IL-22 also induces MCP-1 production in autoimmune settings such as rheumatoid arthritis." (PMID 27166675, 2016). "In addition, it is quite clear that VDR ligands directly target also Th17 cell subtype, as shown by the reduction of Th17 cytokines, such as IL-17A, IL-17F, and IL-22 by memory T cells in patients with early rheumatoid arthritis (RA)." (PMID 24895631, 2014). "We conclude that IL-22 expression level was increased and correlated with disease severity, which indicated that IL-22 may play an important role in development of PIA, and was helpful to explorer the pathogenesis of rheumatoid arthritis." (PMID 29182672, 2017). "The rheumatoid arthritis (RA) milieu polarizes CD4+ T cells to the pro-inflammatory T helper (Th) 17 phenotype with increased secretion of IL-17 and IL-22." (PMID 40852730, 2025). "Preclinical and clinical studies have demonstrated that a human anti-IL-22-mAb (fezakinumab) and IL‐22R1‐targeting mAbs are currently tested as a treatment for several inflammatory diseases such as rheumatoid arthritis and severe atopic dermatitis, without obvious adverse safety concerns observed." (PMID 34388961, 2021). "The present study aimed to evaluate the suppressive role of interleukin (IL)-25 in IL-22-induced osteoclastogenesis and receptor activator of nuclear factor κB ligand (RANKL) expression in rheumatoid arthritis (RA)." (PMID 32972460, 2020). "In rheumatoid arthritis (RA), high protein levels of IL-23 and IL-17F were detected in the synovial fluid of patients displaying ectopic lymphoid follicles, and a positive correlation was observed between CD21L mRNA (as a TLS marker) and IL-23 but also IL-17F, IL-21, and IL-22 mRNAs." (PMID 27752258, 2016). "In rheumatoid arthritis (RA), IL-22 responses are increased in peripheral blood and joints, IL-22 induces RANKL, and the magnitude of IL-22 response correlates with inflammatory markers (ESR and CRP), RA disease activity scores and degree of bone damage." (PMID 24676270, 2014). "In this review, we will discuss the pathogenesis of IL-22 and potential therapy targets in connective tissue diseases such as systemic lupus erythematosus (SLE), rheumatoid arthritis (RA), Sjogren’s syndrome (SS), dermatomyositis, and systematic sclerosis (SSc)." (PMID 33407883, 2021). "A previous in vitro study on patients with rheumatoid arthritis observed that TNF blockade does not suppress the production of IL-17A and IL-22." (PMID 39409006, 2024).
atopic dermatitis (85 papers, 2011 to 2025). "Atopic dermatitis, in contrast, is believed to be mediated by Th2 and Th22, and the associated secretion of IL-4/IL-13 and IL-22, respectively." (PMID 37138890, 2023). "Here, the CD8+ T cells upregulated the secretion of IL-22, indicating that this cell type is less susceptible to S. aureus enterotoxins and is responsible for skin pathogenesis in atopic dermatitis patients." (PMID 33003458, 2020). "Interleukin-22 (IL-22), a cytokine of the IL-10 family, has emerged as a promising therapeutic target in atopic dermatitis (AD)." (PMID 40666509, 2025). "Current understanding of IL-22 in atopic dermatitis (AD) mostly relies on animal models, intracellular staining of polyclonally activated peripheral lymphocytes, and biological therapies." (PMID 40666509, 2025). "Our study examined the Th22/IL-22 pathway, which is known to disrupt the skin barrier and exacerbate pruritus in atopic dermatitis." (PMID 41268562, 2025). "Increased blood and skin IL-22 levels have been reported in patients suffering from atopic dermatitis." (PMID 38541978, 2024). "Another important interleukin in the pathogenesis of atopic dermatitis is IL-22, which is synthesized and released by CD4+ T cells, ILC type 3 (ILC3), γδ+ T cells, natural killer (NK) cells, CD8+ T cells, and dendritic cells (DC)." (PMID 38541978, 2024). "These patients were also enriched for a 296 gene signature obtained from atopic dermatitis patients who were clinical super‐responders to the anti‐IL‐22 antibody, Fezakinumab." (PMID 39073027, 2024). "Known biomarkers of atopic dermatitis include IL-22 (Interleukin-22), IL-18, and IL-13, as well as eosinophilia and elevated IgE levels." (PMID 39457662, 2024). "The immunology of chronic prurigo shows similarities with atopic dermatitis due to the involvement of IL-4 and IL-13, IL-22, and IL-31." (PMID 38493053, 2024). "Numerous Studies demonstrated that increased expression of IL-22 was correlated with the Scoring of Atopic Dermatitis (SCORAD)." (PMID 35911703, 2022). "Th2/Th17/Th22 cytokine elevation has been observed in a subset of patients with atopic dermatitis, and the IL-23-IL-17 axis and IL-22 have been targeted by monoclonal antibodies for the treatment of atopic dermatitis." (PMID 35757747, 2022). "A recent Phase 2 clinical trial showed the efficacy of an IL‐22‐neutralizing antibody (fezakinumab) in atopic dermatitis." (PMID 34459137, 2021). "The role of IL-22 has been investigated in a model of atopic dermatitis and allergic asthma in which mice are epicutaneously sensitized to the model antigen ovalbumin followed by intranasal challenge." (PMID 33692792, 2021). "Similar results to our study were obtained by Kanda and colleagues, who showed that 1.25(OH)2D3 inhibits the secretion of IL-22 in patients with atopic dermatitis." (PMID 33435598, 2021). "Currently,the safety, tolerability and therapeutic effects of Fezakinumab (ILV-094), a human monoclonal antibody that directly binds to IL-22, have been examined in atopic dermatitis patients in severalclinical studies." (PMID 34295334, 2021). "Specifically, in S. aureus infections affecting atopic dermatitis patients, secreted enterotoxins can inhibit the production of IL-22 from CD4+ T cells." (PMID 33003458, 2020). "IL-22 also promotes epidermal barrier disruption and pruritus and has been reported to play a role in the pathogenesis of atopic dermatitis." (PMID 31781680, 2019). "Currently, blocking IL-22 with anti-IL-22 monoclonal antibody is in in phase 2a trial for treatment of atopic dermatitis; moreover, delivery of the murine IL22ra2 gene by cationic micelles has displayed promising potential for colon cancer therapy." (PMID 30619294, 2018). "In this study, we aimed to evaluate the potential role of staphylococcal enterotoxins (SEA and SEB) in modulating IL-22 producing CD4+/CD8+ T cells in adults with atopic dermatitis." (PMID 29703987, 2018).
atopic dermatitis (continued). "Consistent with this notion, Malassezia-reactive skin homing T cells from Malassezia-sensitized atopic dermatitis patients comprise not only Th1 and Th2 subsets but also IL-17- and IL-22-secreting cells." (PMID 29213272, 2017). "In inflammatory conditions, such as atopic dermatitis and psoriatic skin lesions, Tc22 numbers increase and contribute to the disease pathology due to their pro-inflammatory actions, such as overproduction of IL-22, IL-17, and IFN-γ." (PMID 41009359, 2025). "Skin biopsy specimens from Asian children with atopic dermatitis express significantly higher levels of T helper Th17‐ and Th22‐related cytokines (especially interleukin (IL)‐17A, IL‐19, and IL‐22) and IL‐17/IL‐22 than found in skin biopsy specimens from European American children." (PMID 36705040, 2023). "Interestingly, recent work suggests that IL-17/IL-22 responses are particularly elevated in pediatric atopic dermatitis." (PMID 35265075, 2022). "Beyond the homeostatic functions of IL-17 and IL-22, Th17 response is known to be involved in several chronic inflammatory diseases such as rheumatoid arthritis, psoriasis, psoriatic arthritis, ankylosing spondylitis, Crohn's disease, and atopic dermatitis." (PMID 35386663, 2022). "Anti-IL-22 Ab has shown promise in the treatment of patients with atopic dermatitis." (PMID 34868019, 2021). "We think that the increase of inflammatory ILC3s and the cytokines, IL-17 and IL-22 initiated in the gut may trigger the various inflammatory responses that progresses to atopic dermatitis." (PMID 34162906, 2021). "The treatment effects of Fezakinumab are particularly evident in patients with high IL-22 baseline expression, suggesting that a precision medicine-based approach might be needed for improving therapeutic outcomes in patients with atopic dermatitis." (PMID 34295334, 2021). "Whether and how IL-17 and/or IL-22 may contribute to pathogenicity in atopic dermatitis remains to be determined." (PMID 29213272, 2017). "IL-22, TNFa, IL-4, and IL-13 combination is able to mimic an “atopic dermatitis like” state." (PMID 23193414, 2012). "IL-22 is involved in atopic dermatitis and may be relevant in the atopic march." (PMID 35203504, 2022). "Finally, we included a study that explored an innovative strategy by searching for gene signatures of atopic dermatitis in severe asthmatic, trying to identify who could benefit from anti-IL-22 antibody treatment." (PMID 35203504, 2022). "In a phase IIa trial in patients with atopic dermatitis, IL-22 levels were correlated with disease severity measures at baseline: Eczema Area and Severity Index (EASI; p<0.0001) and SCORing Atopic Dermatitis (SCORAD; p=0.001)." (PMID 39483464, 2024). "In atopic dermatitis pathogenesis, inflammatory cytokines of the Th2, Th17, Th1, and Th22 subclasses, such as IL-4, IL-13, IL-17A, INF-γ, IL-12A, and IL-22, play important roles." (PMID 38672764, 2024). "Vα7.2+/CD161− T cells in atopic dermatitis exhibited a decrease in CD8 and IFNγ-producing subsets but an increase in CD38 activated and IL-22-producing subsets." (PMID 38542456, 2024). "While the Th2 cytokine IL-4 is important for acute atopic eczema development, the Th1 and Th17 cytokines IFN-γ, IL-17, and IL-22 predominate in chronic eczema states." (PMID 33520088, 2021). "Th17 cytokine (IL-17 and IL-22) upregulates the expression of CXCL8 and IL-6 in the skin of atopic dermatitis patients and promotes inflammation of the skin." (PMID 28558005, 2017). "In atopic dermatitis, or eczema, the main role is played by T-helper 2 cells and an upregulation of IL-4 and IL-13 is found, in addition to interferon (IFN)-γ, IL-17, and IL-22 in chronic eczema." (PMID 36770889, 2023). "Several blood molecules have been investigated in human studies as potential biomarkers of atopic dermatitis, including TARC/CCL17, macrophage-derived chemokine, IL-22, pulmonary and activation-regulated chemokine, sIL-2R, soluble E-selectin, C-reactive protein, and IL-16." (PMID 34677385, 2021).
atopic dermatitis (continued). "Thus, Tc22, due to its increased cytotoxic action and release of pro-inflammatory cytokines, such as IL-22 and IL-17, regulates TME/TIME and inflammatory processes during viral infections and other inflammatory diseases, such as atopic dermatitis and psoriasis." (PMID 41009359, 2025). "The presence of low levels of Il4 but no detectable Il17 or IL22 suggest that the lesions in our mice may represent a model of atopic dermatitis." (PMID 34445339, 2021).
colon carcinoma (79 papers, 2011 to 2025). "ILC3s and their secretion of IL-22 have been shown to induce the progression of chronic inflammation to colon cancer and association with the perpetuation of colon cancer." (PMID 39309440, 2024). "In colon cancer, enhanced IL-22 expression is associated with poor prognosis and an enhanced tumorigenesis, with protective role shown by IL-22 binding protein." (PMID 33042126, 2020). "This was implicated in the correlations between IL-22 and several types of carcinoma such as colon cancer and hepatocellular carcinoma." (PMID 32649314, 2020). "In summary, our findings provide a new perspective on the pro-inflammatory cytokine interleukin-22 in promoting aerobic glycolysis associated with tumor progression in human colon cancer cells." (PMID 28445985, 2017). "In 561 colon cancer cases and 722 population controls, an association study suggested that the rs1179251 SNP in IL-22 was associated with the risk of colon cancer." (PMID 26598081, 2015). "Furthermore, the inflammasome-induced downregulation of IL-22 endogenous regulators IL-22BP resulted in uncontrolled IL-22 and promoted inflammation-associated colon cancer progression." (PMID 37122757, 2023). "IL-22 has been reported to be a bifacial cytokine in intestinal inflammation, which is not only conducive to mucosal healing, but also increases the risk of colon cancer if overactivated." (PMID 36084127, 2022). "In addition, IL-22 genetic polymorphisms have been shown to be a risk factor for colon cancer, and elevated serum IL-22 levels correlate with chemoresistance in patients with CRC." (PMID 31637216, 2019). "Along with IL-6 and IL-11, elevated levels of IL-22 have been associated with colon cancer." (PMID 30894857, 2019). "While IL-17 and IL-22 are important to maintain intestinal homeostasis and protect against intestinal pathogens, aberrant production of these cytokines has been associated with inflammatory bowel disease and colon cancer." (PMID 23508190, 2013). "Furthermore, excessive activation of the IL-22 pathway may exacerbate intestinal inflammation and potentially increase the risk of colon cancer." (PMID 41019044, 2025). "IL-22 expression is significantly higher in human colon cancer tissue than in healthy tissue and promotes tumor cell proliferation." (PMID 41019044, 2025). "In colon cancer, IL-22 is mainly produced by NCR+ILC3s and then induces STAT-3 phosphorylation and proliferation by interacting with IL-22R on epithelial cells." (PMID 39309440, 2024). "Human colon cancer patients have been observed to have significantly higher levels of IL‐22 in their cancer tissue than healthy controls." (PMID 38363052, 2024). "IL‐22 is found excessively expressed in human colon cancer tissues compared to healthy donor tissues, and in vitro experiments have shown that IL‐22 enhances tumor proliferation." (PMID 38363052, 2024). "In bacteria-induced colon cancer, IL-17 and IL-22-producing colonic ILCs are involved in driving pro-tumor responses; specifically, IL-22 sustains inflammation during cancer by STAT3 phosphorylation in epithelial cells inducing proliferation." (PMID 38567059, 2023). "High levels of IL-22 were detected in colonic cancer tissues, where IL-22 exerted pro-tumoral functions by promoting cancer cell activation of STAT-3, reducing tumor cell apoptosis, and increasing the levels of VEGF in the TME." (PMID 37234993, 2023). "Results of many studies suggest that IL-22 is involved in colon tumor maintenance as the analysis of IL-22 in human colon cancer showed that IL-22 mRNA expression in tumor tissue was more than two-fold higher than in normal tissue." (PMID 37176567, 2023). "Previous research showed that lncRNA LINC00662 overexpression targeting miR-340-5p/CLDN8/IL22 axis promoted proliferation, migration, and invasion and suppressed apoptosis of colon cancer cells via activating the ERK signaling pathway in vitro and in vivo." (PMID 35571488, 2022).
colon carcinoma (continued). "For example, Candida albicans contributed to colon cancer by glycolysis in macrophages, thus triggering the interleukin-22 secretion from innate lymphoid cells." (PMID 35281451, 2022). "Regarding the effect of TGFβ on colon tumor-infiltrating CD4+ T cells, the increased presence of TGFβ in sporadic colon tumors was obviously accompanied by the augmented presence of IL-17A+ IL-22+ CD4+ T cells." (PMID 36428508, 2022). "Another study suggested that LINC00662 competitively binds to miR-340-5p to modulate the expression of CLDN8/IL22 in colon cancer." (PMID 34048366, 2021). "Depletion of IL‐17+IL‐22+ colonic innate lymphoid cells prevented the development of invasive colon cancer." (PMID 34496133, 2021). "In recent years, several studies have demonstrated that excessive IL-22 was present in human colon cancer." (PMID 35154603, 2021). "On the other hand, another study demonstrated a protective role of IL-22 in inflammation-induced colon tumors by improving the cellular response to DNA damage." (PMID 33692792, 2021). "Its overexpression promoted the occurrence and development of colon cancer by competitively binding with miR-340-5p to regulate CLDN8/IL22 co-expression and activating ERK signaling pathway." (PMID 34659345, 2021). "Stem cells that were exposed to carcinogens and deprived of IL-22 signals evaded DDR-directed apoptosis, accumulated mutations, and were prone to colon cancer onset." (PMID 33513745, 2021). "On the other hand, enhanced IL-22 expression can extend tissue regeneration process and also stimulate the development of colon cancer." (PMID 33042126, 2020). "Key cellular sources responsible for producing IL-22 in the setting of colon cancer include ILCs and Th22 cells." (PMID 33042126, 2020). "LINC00662 overexpression promoted the occurrence and development of colon cancer by competitively binding with miR-340-5p to regulate CLDN8/IL22 co-expression and activating ERK signaling pathway." (PMID 31900207, 2020). "In colon cancer, deletion of IL‐22 gene reduced the tumor number as well as overall tumor burden in the intestine." (PMID 31725949, 2020). "At the molecular level, IL-22 promotes carcinogenesis of colon cancer cells by activating STAT3, AKT, MAPK, and NFκβ." (PMID 33042126, 2020). "The results showed that BALB/c nude mice transplanted subcutaneously with RKO colon cancer cells tended to have faster tumor growth after intraperitoneal injection of IL-22 every other day, compared to that of control mice." (PMID 31637216, 2019). "By using an immunodeficient Rag−/− mouse model, it has been shown that NKp46−CD4−ILC3 accumulation leads to IL-17 and IL-22 production, which promotes tumor development, whereas depletion of ILCs with anti-Thy1 mAbs limits tumor growth in colon cancer." (PMID 32117199, 2019). "The ability of IL-22 to promote the production of functional Muc1 through activation of STAT3 has been demonstrated using human colonic cancer cell lines (T84 and HT29) and primary colonic epithelial cells from mice." (PMID 29075900, 2018). "In accordance with our findings, it has been previously determined that excessive IL-22 production leads to tumor growth in colon cancer as well as apoptosis inhibition through STAT3 activation." (PMID 30235866, 2018). "In fact, Kryczek and coworkers showed that IL-22 acts on colon cancer cells inducing STAT3 activation and the expression of the histone methyltransferase DOT1L." (PMID 29652830, 2018). "More recently, evidence was provided of an important role in colon cancer progression and stemness maintenance of another cytokine, IL-22." (PMID 29652830, 2018). "Herein, we report that cultivation of human DLD1 and Caco2 colon carcinoma as well as HepG2 hepatoma cells under the influence of hypothermia amplifies initial IL-22 signal transduction." (PMID 28706520, 2017).